COL5A2 (collagen type V alpha 2 chain)
Diseases named in the same sentence as COL5A2 in open-access papers (continued):
Sharing a sentence is not in itself a finding about the gene and the disease.
tumor (74 papers, 2009 to 2026). "COL5A2 protein expression was found to be elevated in tumor tissue and associated with worse overall and disease-free survival." (PMID 42072830, 2026). "For example, FABP4 showed high expression in tumour surrounding adipocytes and COL5A2 was expressed in tumour-associated fibroblasts." (PMID 38361045, 2024). "While COL5A2 was involved in the "epithelial‐mesenchymal transition" related hallmark, which promoted tumor cell invasion and metastasis." (PMID 33078899, 2020). "The co-expressed genes of COL5A2 were associated with tumor stage or poor survival." (PMID 37723519, 2023). "GSEA analyses revealed that COL5A2 was associated with tumor progression-related pathways." (PMID 37723519, 2023). "Moreover, the further investigation suggested that COL5A2 expression was associated with tumor-infiltrating immune cells, immune marker sets and immune checkpoint molecules, and may affect the immunotherapy response." (PMID 37723519, 2023). "Also, the interactions between COL5A2 and immune cells in the tumor microenvironment indicated that COL5A2 could be an underlying immunotherapy target in PCa." (PMID 33816226, 2021). "In ROC analyses, COL5A2 exhibited stable tumor-versus-non-tumor discrimination across GSE15471, GSE16515, and GSE62452 (AUC = 0.932, 0.760, and 0.782, respectively) and significantly outperformed COL3A1 in two cohorts." (PMID 42072830, 2026). "Specifically, NUCB2, SCGN and IFI6 were markedly upregulated in cells from the tumour centre, whereas COL5A2 was significantly downregulated in this region." (PMID 40913484, 2025). "Overexpression of COL5A2 has been detected in patients with gastric, prostatic, and colorectal malignancies, and thus can predict the prognosis of tumor patients." (PMID 39995998, 2025). "COL5A2 modulates tumor development, progression, and treatment response by affecting various components of the tumor microenvironment, such as the extracellular matrix, immune cell function, and angiogenesis." (PMID 39995998, 2025). "For example, collagens, such as COL1A1, COL1A2, COL3A1, COL5A2, COL6A1, COL6A2, and COL6A3 are thought to mediate tumor progression and are associated with a poor prognosis in BCa." (PMID 37277784, 2023). "Research shows that increased expression of COL5A2 is associated with increased expression of cytokines such as VEGF, which lead to the growth of tumor cells and unrestricted angiogenesis." (PMID 37361568, 2023). "Firstly, to fully evaluate the significance of COL5A2 in various solid tumors, pan-cancer analysis was conducted to compare COL5A2 mRNA expression levels between tumor samples and normal samples of the TCGA-STAD through the TIMER2.0 database." (PMID 37723519, 2023). "As a member of the collagen family, V-type α2 collagen (COL5A2) affects tumor angiogenesis and metastasis." (PMID 37988196, 2023). "The area under the curve of COL5A2 was 0.917, which indicates that COL5A2 has a certain accuracy in predicting tumor and normal outcomes." (PMID 36447214, 2022). "In contrast, COL5A2, a member of the collagen family, is involved in immune system regulation, angiogenesis, and tumor metastasis, and plays a role in promoting tumor progression." (PMID 35280775, 2022). "More importantly, COL5A2 was correlated with stromal scores in GC, promoted the recruitment of circulating monocytes into the TME, and facilitated their differentiation into tumour-associated macrophages." (PMID 36452120, 2022). "Tumor genes COL5A2 and ITGAV expression also correlated with overall survival in the epithelioid subtype, demonstrating that epithelioid MESO can acquire EMT characteristics affecting survival before being categorized as biphasic." (PMID 35046456, 2022).
tumor (continued). "Type V collagen α2 chain (COL5A2) plays important roles in immune system regulation, angiogenesis and tumor metastasis, and participates in the occurrence and development of colorectal cancer, breast cancer and osteosarcoma." (PMID 36447214, 2022). "Risk factors, like STC1, COL5A2, COL3A1, and BGN, were significantly correlated with poor OS, while BMPR2 and PGLYRP1 were only found to be protective factors in 2 of 33 tumor types." (PMID 36479101, 2022). "We found that COL1A2, COL3A1, COL5A2, tumor mediators targeting of relevant structural components of the extracellular matrix (ECM) were activated to drive CAFs to synthetize fibrillar collagen creating an aberrant microenvironment." (PMID 34458147, 2021). "Many studies have demonstrated that COL5A2 is differentially expressed in various tumors and is related to tumor metastasis and poor prognosis." (PMID 33816226, 2021). "Other mutations within PyMT E2F1 KO tumors include COL5A2, with collagen V being a component of the interstitial matrix, COL6A1-3, with collagen VI being abundant in the tumor invasive front and several integrin and cadherin genes." (PMID 33947907, 2021). "The results indicated that the samples with high COL5A2 expression were correlated with high immune infiltration in the tumor microenvironment." (PMID 33816226, 2021). "Among these genes, COL1A1, COL1A2, FN1 and COL5A2 were considered as perspective effective targets that play prominent roles in the development and recurrence of the tumor, including STAD." (PMID 33193601, 2020). "Additionally, COL5A2 expression correlated with increased tumor cell invasion and resistance to androgen deprivation therapy." (PMID 38672562, 2024). "In addition, we found that COL5A2 expression correlated with immune cell marker genes, which indicated that COL5A2 was involved in regulating tumor immunology." (PMID 37723519, 2023). "In addition, GSEA analyses revealed that in the high-COL5A2 expression group, tumor progression-related pathways, including angiogenesis, IL6-JAK-STAT3 signaling as well as Notch signaling were enriched." (PMID 37723519, 2023). "The AUC value at 5 years of COL5A2 expression was higher than that of age and tumor stage." (PMID 37723519, 2023). "Meanwhile, COL5A2 expression was correlated with tumor-infiltrating immune cells." (PMID 37723519, 2023). "Since COL5A2 expression was related to tumor stage as well as the prognosis of GC, we hypothesised that upregulated COL5A2 could promote tumor progression." (PMID 37723519, 2023). "Based on tumor grade, COL5A2 expression varied in grades I, II, and III subgroup patients." (PMID 36712590, 2023). "Considering that COL5A2 expression affects TME immune cell infiltration and may promote tumor cell immune escape, we further analyzed whether COL5A2 expression could assess the response to immunotherapy." (PMID 37723519, 2023). "Moreover, GSEA was conducted and found that there was a dynamic correlation between high COL5A2 expression and hallmarks of tumor such as “angiogenesis”, “IL6-JAK-STAT3 signaling” and “NOTCH signaling”." (PMID 37723519, 2023). "Several studies have reported that COL5A2 might play a crucial role in the initiation and progression of tumours using bioinformatics technologies." (PMID 36452120, 2022). "A mechanistic study elucidated that COL5A2 might accelerate tumor progression through hypoxia, coagulation, apical junction, angiogenesis, and apoptosis." (PMID 36471693, 2022).
tumor (continued). "We found that COL5A2 may regulate chemicals and human diseases and it is related to tumor treatment drugs." (PMID 36263088, 2022). "Immune infiltration analysis suggested that COL5A2 might influence the changes in the tumor immune microenvironment." (PMID 36447214, 2022). "Tumor cell genes COL5A2 and ITGAV expression correlated with overall survival in MESO cohort." (PMID 35046456, 2022). "Experimental results suggested that COL5A2 is highly expressed in high Gleason score PCa tissues and could promote tumor proliferation and invasion." (PMID 33816226, 2021). "This indicated that high COL5A2 expression may promote the immune escape of tumor cells in GC." (PMID 37723519, 2023). "In addition to promoting cell proliferation, COL5A2 also promotes tumor progression." (PMID 35497183, 2022). "Furthermore, WB experiments confirmed that COL5A2 could achieve tumor suppression by inhibiting the TGF-β signaling or Wnt/β-catenin signaling pathways." (PMID 35280775, 2022). "In addition, many tumor-related substances or drugs can affect the expression of COL5A2." (PMID 36263088, 2022). "In CRC, the COL11A1 gene is excessively expressed and contributes to tumor advancement by upregulating other genes like THBS2, COL10A1, COL5A2, and COL1A2, thereby driving neoplasia." (PMID 40109582, 2025). "Overexpression of collagen genes (COL1A1 and COL5A2) and dysregulation of ECM enzymes further highlight the stromal contribution to tumor aggression." (PMID 40507957, 2025). "COL5A2 and COL6A1 have been identified through pan-cancer analyses as significant factors in prognosis and tumor microenvironment modulation." (PMID 41139924, 2025). "COL5A2, HMGCS2 and ITGA5 expressed in the tumour compartment and cytoplasmatic as well as WNT9Bnuc in the stroma were favourable prognostic factors for OS (p < 0.05) in univariate analysis." (PMID 38361045, 2024). "In particular, CTHRC1+GREM1+ myCAF expressed high levels of collagens, including type-1 (COL1A1, COL1A6), type-3 (COL3A1), type-5 (COL5A2), and type-6 (COL6A1), which contribute to tumor cell migration and proliferation through collagen/integrin interactions." (PMID 39075108, 2024). "The TCGA and GETx datasets indicated that COL1A1, COL3A1, COL5A2, COL8A1, COL10A1, and COL12A1 genes were expressed much higher in tumor tissues than in the normal ones." (PMID 36900272, 2023). "Identification of collagen genes COL5A1, COL5A2, and COL3A1 as top key regulators points to a tumor microenvironment with significant fibrosis and desmoplastic change." (PMID 36637997, 2023). "The extracellular matrix (ECM) includes fibrillar collagens (e.g. COL1A1, COL5A2, COL11A1) as the major connective tissue components and tumor microenvironment." (PMID 36587397, 2023). "Not only were many collagen genes overexpressed in tumor progression between T1 and T2 stages, but also the mRNA expression of these collagen genes, such as COL1A1, COL1A2, COL3A1, COL5A1, COL5A2, COL6A2, and COL6A3, was highly positively correlated." (PMID 36596829, 2023). "High expressions of tumor cell genes COL5A2 and ITGAV and non-tumor cell genes SPARC and ACTA2 are both positively correlated with poor overall survival and disease-free survival in MESO cohort." (PMID 35046456, 2022). "Col1a1, Col1a2, Col2a1, Col3a1, and Col5a2, which were commonly found in normal ECM of mouse, pig, and human breast tissues, were also identified in tumor ECM in addition to Col4a2, Col5a1, Col6a1, Col6a2, Col6a3, and Col7a1." (PMID 36547361, 2022).
tumor (continued). "The MIR4435-2HG- and ELFN1-AS1-associated ceRNA subnetworks affected and regulated the expression of the COL5A2, LOX, OSBPL3, PLAU, VCAN, SRM, and E2F1 target genes and were found to be related to prognosis and tumor-infiltrating immune cell types." (PMID 33750326, 2021). "The key genes COL1A1, COL4A1, COL5A2 belong to the collagen family, which is a constituent of the ECM component of tumors, and is closely related to tumor proliferation, invasion, drug resistance, and prognosis 7,40-46." (PMID 33976737, 2021). "The GS value of ANGPT2 to tumor grade was 0.909, P= 0.006 (SERPINE1, P= 0.025; HS3ST2, P= 0.103; COL1A1, P= 0.040; COL5A2, P= 0.006)." (PMID 33758610, 2021). "The gene list they identified shares similarities to gene expressed in our whole tumour sample (ANTXR1, COL12A1, COL5A2, CTHRC1, POSTN)." (PMID 19401702, 2009). "High COL5A2 expression was detected in GC tissues (42.5%, 17/30), but not detected in adjacent non-tumor tissues (0%, 0/10)." (PMID 37723519, 2023). "We further explored whether the three candidate genes (COL5A2, ezrin, and VIM) were highly specific to clinical OS tumor origin." (PMID 35625426, 2022). "Univariate Cox regression analysis of clinical indicators revealed that T stage, N stage, M stage, pathologic stage, age, histological type, residual tumor, HSPA8P4, PHC1P1, RBMS1P1, LINC01303, and MSC-AS1 were meaningful, and the expression level of COL5A2 was also significant." (PMID 36447214, 2022). "Our in silico study reveals that an abundance of COL11A1 mRNA could induce the transcriptional upregulation of THBS2, COL10A1, COL5A2, and COL1A2 genes cooperatively, to promote the neoplasia." (PMID 33597969, 2021). "We detected 24 genes across the tumor tROIs that showed a high CV (i.e., were among the genes with the top 20% highest CV in seven out of seven cases), such as multiple collagens (COL1A1, COL1A2, COL3A1, COL5A1, COL5A2), S100A8, S100A9, FN1, or Early growth response protein 1 (EGR1)." (PMID 37511126, 2023). "However, the expression of COL5A2 showed no differential expression between tumor and normal tissues." (PMID 33750326, 2021). "In contrast, none of the genes found in tumor fragments to be regulated by translation (LOX, WISP), abundance (FOXC1, COL5A2, ITGA11) or buffering (SNAI2) were modulated by mTORC1 in U87-MG cells." (PMID 31052505, 2019). "Moreover, based on the lack of significantly increased expression of COL5A2 and LAMA4 genes in in vitro tumor cells after TGFβ or β-estradiol treatment, we speculate that signals other than TGFβ or β-estradiol contribute in regulating ECM3 genes." (PMID 23441215, 2013).
cancer (59 papers, 2010 to 2026). A tumor composed of atypical neoplastic, often pleomorphic cells that invade other tissues. "Consistent with our findings, previous research has demonstrated that ECM-related genes, such as COL5A2, exhibit high diagnostic accuracy in other cancers." (PMID 40087784, 2025). "The analyses showed that COL5A2 was associated with T stage and Lauren stage and is involved in cancer-related pathways." (PMID 33739392, 2021). "The COL5A2 gene encodes a 46 kDa nuclear localization transcriptional inhibitor protein that has been reported to affect cancer progression." (PMID 34094925, 2021). "COL5A2, also known as collagen type V alpha 2 chain, has previously been reported to be involved in the pathology of cancer, and the protein encoded by KRT4 is a member of the keratin gene family and is related to differentiation." (PMID 31962291, 2020). "According to the mouse insertional mutagenesis experiments, three of these genes (DMD, MYO9A, and COL5A2) have been identified as cancer-causing genes." (PMID 28938601, 2017). "The ectopic expression of COL10A1 and COL5A2 may affect the development of cancer, leading to genetic mutations and epigenetic alterations." (PMID 33602210, 2021). "Based on a molecular glance, we speculated that COL5A2 expression might be closely linked to cancer invasion." (PMID 30697528, 2018). "Differential expression and co-expression network analysis suggested potential association between COL5A2 expression and essential pathways involved in cancer invasion and dissemination, including cell adhesion, extracellular matrix organization, and epithelial-mesenchymal transition." (PMID 30697528, 2018). "The highest expression of genes encoding Col1a1-2, Col3a1, Col4a1, Col4a2, Col5a1, Col5a2, Col6a1, Col8a1, Col9a3, Col10a1, Col12a1, Col14a1, Col15a1, Col16a1, Col18a1, and Col28a1 were detected in untreated tumors, whose landscapes were dominated by Krt8+ cancer cells." (PMID 39372930, 2024). "Furthermore, some of the positively selected genes might also be related to cancer, such as DMD, MYO9A, and COL5A2, which have been identified as cancer-causing genes based on mouse insertional mutagenesis experiments." (PMID 28938601, 2017). "In GSE43288, COL5A2 expression increased along the normal-pancreatic intraepithelial neoplasia-PDAC axis and remained positively associated with ECM and cancer-associated fibroblast (CAF) signature scores after adjustment for disease group." (PMID 42072830, 2026). "When classified by cancer stages, COL5A2 expression level was notably higher in stages II, III, and IV subgroups than that in stage I and normal subgroups (P < 0.05)." (PMID 36712590, 2023). "Recently, as one of the best-studied collagens, COL5A2 has been reported to be aberrantly expressed in various cancers, such as breast cancer, ovarian cancer, adenomas, and bladder cancer." (PMID 36712590, 2023). "Further results showed that the COL5A2 gene was highly expressed in both cancer subtypes with significantly poorer prognoses." (PMID 36263088, 2022). "By analyzing the tissue expression levels, OS, DSS and PFI of hub genes, we found that COL5A2 was highly expressed in cancer tissues, and the high expression of COL5A2 was significantly correlated with poor prognosis." (PMID 36447214, 2022). "Receiver operating characteristics (ROC) were used to analyze the role of COL5A2 in differentiated carcinoma tissues and normal tissues of GC." (PMID 36447214, 2022). "Among these proteins, the overexpression of MMP14, ITGA2, THBS2, COL1A1, COL3A1, COL11A1 and COL6A3 has been experimentally confirmed in PDAC, while that of COL12A1 and COL5A2 has been shown in other types of cancer." (PMID 34094925, 2021). "There were 340 cells expressing COL5A2, of which only 15 cells were from normal tissues and 325 cells were from cancer tissues." (PMID 34899080, 2021). "In some bioinformatics studies, COL5A2 and COMP have been found to be associated with cancers including GC." (PMID 34899080, 2021).